TNF (tumor necrosis factor)
Diseases named in the same sentence as TNF in open-access papers (continued):
Sharing a sentence is not in itself a finding about the gene and the disease.
tumor (continued). "After the recognition of antigens or other stress-induced molecules expressed on tumor cells by TCR or NKR, γδT cells can mediate the direct tumor lysis by producing granzyme B, perforin, TNF-α and IFN-γ." (PMID 35747139, 2022). "Larger tumor size and/or LN involvement were associated with lower frequencies of CD4+TNF-α+, CD8+IFN-γ+ and CD8+IFN-γ+TNF-α+ but higher frequency of CD4+IL-4+ T cells." (PMID 36376825, 2022). "TNF-α, a prototypical pro-inflammatory cytokine with a broad spectrum of biological functions, was initially recognized only as an inhibitor of tumor cell proliferation and inducer of apoptosis." (PMID 36555705, 2022). "This is important because TNFα possesses strong anti‐tumour activity but induces systemic toxicity and has to be targeted to tumours." (PMID 35758207, 2022). "At the same time, the T cells secrete pro-inflammatory cytokines, such as interferon-gamma (IFN-γ) and tumor necrosis factor alpha (TNF), which can have direct cytotoxic activity on tumor cells, as well as promoting further anti-tumor immune activity." (PMID 35874669, 2022). "CD36 knockout (KO) mice maintain CD8 T cell polyfunctionality through the co-production of IFN-γ and TNF-α, which abrogates tumor growth." (PMID 34983949, 2022). "Tumor-associated-neutrophils can influence macrophage polarization to tumor-associated-macrophages (TAM) by secreting Il-8, TNF-α and MPO." (PMID 35163180, 2022). "The presence of innate immune cells in skeletal muscle tissue in the tumor-bearing state is rarely described, making it unlikely that these cells produce TNFα in the muscle environment." (PMID 36078078, 2022). "For example, FAP causes rapid hypoxic necrosis of both cancer and stromal cells in dependence on IFN γ and TNFα to facilitate anti-tumor T cell infiltration and function, bringing benefits in transplantable models of NSCLC and PDAC." (PMID 35488263, 2022). "Using a linear correlation approach between immunotype and the SGR for each tumor, we observed tumor growth inhibition was most strongly correlated with higher levels of HLA-DR+TIM-3-TNFα+ and TNFα+IFNγ+ CD4+ T cells." (PMID 36419897, 2022). "Neutrophils, under these conditions, expressed cytokines such as TNF-α, Oncostatin M, IL-1β and IL-6, promoting tumour growth." (PMID 35406451, 2022). "For Rnf31 we demonstrate that it protects tumor cells from TNF-mediated caspase 8 cleavage and subsequent apoptosis induction, a mechanism that is conserved in human PDA organoids." (PMID 35379808, 2022). "M1 macrophages promote beneficial anti-tumor effects by driving the Th1 response and via the secretion of TNF-α, IL-1, IL-6, IL-12, Type I IFN, CXCL1-3, CXCL5, and CXCL8-10." (PMID 35345849, 2022). "In the tumor microenvironment, continuous low concentrations of TNF contribute to angiogenesis, which promotes primary tumor growth and metastases, leukocyte infiltration, and pleural effusion." (PMID 35844550, 2022). "In colorectal cancer condition, elevated levels of neutrophils at the primary tumor were correlated with the enhanced NETs in the liver, which also induced proinflammatory cytokine (IL-8, IL-6 and TNF-α) production in trapped cancer cells." (PMID 34835236, 2021). "In both the ABX-treated DSS/Apcmin/+ mice and GF Apcmin/+; Il10−/− mice colonized with NC101, TNF blockade with a TNF monoclonal antibody significantly inhibited tumor development." (PMID 33578830, 2021). "Given that WEHI-164 cells do not express αvβ3 receptors, these results also suggest that the improved anti-tumor activity of 1-Au/TNF was mediated by targeted delivery of TNF to a tumor stroma component, likely to αvβ3-positive endothelial cells." (PMID 34124009, 2021). "Remarkably, within the tumor microenvironment, TNF-α increase activates NF-kB in cancer cells, leading to the further increase of deubiquitinase CSN5 (COP9 signalosome 5) expression which inhibits PD-L1 degradation, facilitating immune escape of cancer cells." (PMID 34638337, 2021).
tumor (continued). "APRIL is a new member of the tumor necrosis factor, which is reported to stimulate tumor cell growth, modulate tumor cell apoptosis, and regulate humoral immunity." (PMID 34220120, 2021). "The anti‐tumor effect of ‘SM‐only treatments’ depends on the ability of cancer cells to produce TNF and exert a cytotoxic response to this death ligand." (PMID 33484626, 2021). "In these mice received low-dose decitabine-pretreated CD4+ T cells, the expression levels of cytotoxic marker granzyme B and TNF-α were also upregulated in tumor infiltrated CD4+ T cells." (PMID 33791306, 2021). "To explore the effect of BJJP on the HCC tumor inflammatory microenvironment, we further analyzed the expression of TNF-α in mice serum using Elisa assay." (PMID 33762939, 2021). "Similar to other factors generated during inflammation (ROS, for example), TNF-alpha has tumor-destructive and tumor-promoting properties, which appear to depend on the receptor (TNFR1 vs. TNFR2) and the amount of TNF." (PMID 35048056, 2021). "Here, we found that tumor necrosis factor α (TNFα) produced by CAR-T cells upon tumor recognition and interleukin 1β (IL1β) secreted by activated myeloid cells were the main cytokines in inducing endothelial activation." (PMID 34093519, 2021). "It is well known that the clinical application of INFγ and TNFα is difficult due to their severe systemic toxicity in spite of strong anti-tumor effects." (PMID 34204302, 2021). "Hypo-fractionated radiation alsoinduces cell death by upregulating Fas and many other cytokines such as interleukin (IL)-2, IL-1α, IL-1β, IL-12, and tumor necrosis factor (TNF)-α involved in the initiation of an adaptive anti-tumor immune response." (PMID 34439390, 2021). "TNF-α and IL-1β cause an increase in the transcription factor glioma-associated oncogene homolog (GLI) present in tumor cells, and consequently activate the hedgehog (Hh) pathway." (PMID 33670011, 2021). "IL6 and TNFα promote tumor angiogenesis through increasing vascular endothelial growth factor (VEGF) expression." (PMID 33579265, 2021). "The astrocyte-tumor interaction increases the expression of receptors for IL-6 and its subunit gp130 and decreases the receptors for TNF-α and IL-1β on HARA-B metastatic lung squamous carcinoma cells." (PMID 33466236, 2021). "SMAC mimetic compounds (SMCs) are small molecule mimetics of this cellular factor that can potentiate TRAIL- and TNF-α-mediated cell death, especially in tumor cells where theses signaling pathways are aberrant." (PMID 34298601, 2021). "In models of dormancy, IL-1β together with TNF-α stimulated the reactivation and proliferation of tumor cells within an osteoblastic matrix." (PMID 34064859, 2021). "The recipients of cecal contents from the anti-TNF-treated mice revealed significantly lower tumor numbers than the recipients of cecal contents from the PBS-treated mice." (PMID 33578830, 2021). "The results showed that the butanol extract significantly promoted the activation of macrophages and upregulated the production of TNF-α and nitric oxide in tumor cells." (PMID 34992527, 2021). "In contrast, M1 macrophages are activated by Th1 cell factors; secrete inducible inductors, such as IL-12, iNOS, and TNF-α; and play a proinflammatory and antitumor role in the tumor microenvironment." (PMID 34888385, 2021). "We show that cigarette smoke is able to promote production of pro-inflammatory cytokines such as TNF-α and IL-8, which can play pro-tumor roles in the tumor microenvironment." (PMID 33754052, 2021). "Infliximab inhibits tumor growth and lymph node metastasis by combining molecular pathways mediated by TNF-α." (PMID 34388989, 2021). "Inflammatory cytokines like interleukin 6 (IL‐6) and tumour necrosis factor‐α (TNF‐α) released from tumour cells or the tumour microenvironment play a central pathophysiological role." (PMID 34636159, 2021).
tumor (continued). "TNF-α plays important roles in various biological processes, such as immunomodulation, fever, inflammatory response, inhibition of tumor formation, and inhibition of virus replication." (PMID 34395451, 2021). "Tip-DCs mediate NO production via interaction with CTLs, resulting in enhanced tumor-killing activity through TNF and NO production." (PMID 33499256, 2021). "On the other hand, TNFα is a key inflammatory cytokine produced by macrophages, T cells, B cells, and NK cells, in addition to tumor cells." (PMID 34573003, 2021). "TNF-α, IL-6, IL-1, and chemokines induce tumor growth by promoting angiogenesis and suppressing immune-mediated tumor elimination, while dendritic cells (DCs) and natural killer (NK) cells play a critical role in the early defense against cancer." (PMID 34068653, 2021). "T cells from tumor-bearing mice immunized with VP1/CA or VP1/RA shown increased secretion of IL-2, IFN-γ, and TNF-α than T cells from untreated tumor-bearing mice in this study, which were correlated with in vivo antitumor effects induced by VP1/CA or VP1/RA." (PMID 34611173, 2021). "It has been shown that certain tumours produce chemotactic agents, such as TNFα; IL‐17; CXCR2 ligands CXCL1, CXCL2, CXCL5, and CXCL6, to attract neutrophils." (PMID 33665979, 2021). "We found that TNFα expression in tumor models was upregulated by bisphosphonates, as described for other physiological systems." (PMID 34327193, 2021). "Cytotoxic T cell exerted antitumor effects via cytokine production, such as IFN-γ, TNF-α, granzyme B, and perforin, under the specific tumor antigen stimulation." (PMID 34381711, 2021). "Neurotransmitter substance P (SP) (a member of the tachykinin neuropeptide family), secreted by both tumor and stromal cells, is known to induce many cytokines (IL-1, IL-6, TNF-α)." (PMID 33925575, 2021). "The identification of potent, anti-tumor cytokine, TNF-α, dramatically induced in pulmonary ILC2s is vitally important for a cell that is uniquely positioned to act as the first responder during tumor infiltration." (PMID 34531874, 2021). "To investigate this, we exposed primary cultures of peritumoral CD90+CD73+ cells (LUSC, n = 8; and LUAD, n = 8, biological replicates) to TNFα and IFNγ, two pro-inflammatory cytokines that feature prominently in inflamed tumours." (PMID 34740105, 2021). "The M1 microphage markers TNF-α and HLA-DR were greatly downregulated in tumor tissues, compared with para-carcinoma tissues." (PMID 34506209, 2021). "Blockage of PD-L1 can restore IFNγ/TNF-α production in BTLAPD-1 tumor CD4+T cells, but partially inhibit the activation of BTLAPD-1 CD4+T cells." (PMID 34869376, 2021). "A large number of studies indicate that TNFα and IL-1β promote disease progression by acting directly on the tumor cells and by affecting different components of the TME, including immune cells." (PMID 33806906, 2021). "Since TNF-α treatment induces high systemic toxicity, it can only be used as a tumor therapeutic agent under conditions where the systemic TNF-α action was reduced or prevented." (PMID 33961948, 2021). "Lymphocytes are the leading components of immunity against tumors, stimulating the release of cytokines such as interferons and tumor necrosis factor-alpha, which results in subsequent tumor reduction." (PMID 34406270, 2021). "Tumor necrosis factor (TNF) is a cytokine that is mainly produced by Macrophages and has crucial roles in tumor development and tumor progression inducing apoptosis, necrosis, angiogenesis, immune cell activation, differentiation, and cell migration." (PMID 33757216, 2021). "Tumor-bearing mice had significantly elevated hepatic expression of the pro-inflammatory cytokines IL-1α, IL-1β, TNF-α, Cxcl9, and Cxcl10 compared to tumor-free mice." (PMID 34445729, 2021). "In tumor-free mice, neutrophils exhibit high levels of phagocytosis and express high levels of lysosomal enzymes and TNF-α." (PMID 34359674, 2021).
tumor (continued). "Other studies showed that autonomous TNF-α-NF-κB and IL-6-STAT3 signaling are essential for tumor growth while ADAM17 turn on the signaling cascade by the shedding of TNFα." (PMID 34182543, 2021). "The key molecules stimulating tumor growth and invasion induced by these bacteria include IL-6, cyclin D1, TNFα, MMP9 and heparanase." (PMID 33823861, 2021). "Dectin-1 derived from particulate β-glucan converted M2 bone marrow-derived macrophages into M1-like phenotype, which expresses proinflammatory cytokines such as TNF-α, iNOS, IL-1β, and IL-6 to inhibit the development of the tumor." (PMID 34094602, 2021). "TNF-α signaling also positively affects immune activation in the tumor microenvironment through a positive feedback mechanism between TNFα levels and M1 macrophage activation." (PMID 33767579, 2021). "Conversely, TNF-α has been shown to inhibit anti-tumor immune responses through modulating leukocytes and altering cancer cell phenotypes during cancer progression." (PMID 33961948, 2021). "Upon laser irradiation, the heat generated by PTT relieved the TcI repression and initiated the expression of TNF-α to induce the apoptosis of tumor cells." (PMID 34158866, 2021). "The TNF-α protein induces the expression of adhesion molecules, facilitating the invasion of metastatic tumor cells, the observation of high levels of TNF-α have been recorded in the blood of some cancer patients." (PMID 33773554, 2021). "M1 macrophages possess antitumor activities by producing pro-inflammatory cytokines, such as IL-1β, IL-6, and TNF-α, while M2 macrophages possess pro-tumor activities by producing anti-inflammatory cytokines, such as IL-10, IL-13, and TGF-β." (PMID 33230600, 2021). "In another study, the Salmonella Typhi vaccine strain CVD 915, orally administered to BALB/c mice, elicited a T-cell mediated immunity by increasing IFN-γ and TNF production in the tumor, resulting in a reduced number of liver metastases." (PMID 34207850, 2021). "Prophylactic treatment with anti-TNF increased the infiltration of tumour-specific CD8 T cells in mice tumours and ameliorated autoimmune colitis." (PMID 34964025, 2021). "PD-1 on TI DCs from human ovarian cancer patients and mouse tumor tissues suppresses cytokine production (TNF-α and IL-6) and costimulatory molecule expression (CD40 and CD80)." (PMID 34901012, 2021). "The level of TNF-α in the lungs of tumor-bearing mice and mice treated with cryo-thermal therapy with TNF-α supplementation was much higher than that after cryo-thermal therapy alone." (PMID 34576115, 2021). "The authors went on to show that CAR T cells directed at B7-H3 are capable of crossing the BBB and produce sufficient tumour-killing amounts of IFNγ, IL-2 and TNFα when cocultured with DMG cells." (PMID 34944870, 2021). "PD-1/PD-L1 and CD8 T cells are closely related, as PD-1 blockade can increase CD8 T cell and tumor-specific interferon-γ production in the tumor microenvironment or produce anti-tumor effects by increasing KLRG1 + LAG3 - TNFα+ tumor-specific T cells in tumors." (PMID 34439378, 2021). "In most cancers, the activation of NF‐κB is enhanced, and this enhancement in NF‐κB activation is often due to increased stimuli of the NF‐κB pathway, such as increased TNFα and IL‐1 in the tumor microenvironment." (PMID 34977871, 2021). "In vitro, the nanomedicine successfully promoted M1 marker TNF-α almost twenty times more than the control and reduced the tumor burden in mice." (PMID 34944555, 2021). "Indeed, pivotal pro-inflammatory cytokines, including tumor necrosis factor-α (TNF-α) and interleukin-1β (IL-1β), may be secreted by tumor-associated macrophages to further promote tumor cell growth, migration, invasion, and the epithelial to mesenchymal transition, mainly via the NF-κB pathway." (PMID 34046348, 2021). "In cancer, TNF-α has had dual roles and in addition to promoting cancer through chronic inflammation, also has direct cytotoxic effects and stimulates anti-tumor immunity." (PMID 34063789, 2021).
tumor (continued). "The inhibition of these signal transduction events ultimately leads to a reduction in the TNF-α-induced invasiveness of the tumor cells in this study." (PMID 33670434, 2021). "Secreted by tumor infiltrating macrophages (tumor microenvironment), TNFα was suggested to activate SphK1, stimulate the expression of S1P3, and promote the development of cancer cell resistance and metastasis in a subset of TNFα-resistant cells." (PMID 33919234, 2021). "Tumor tissue showed a high amount of IFNγ, IL-6, and TNFα, which is consistent with a phenotype of TIL activation." (PMID 33986267, 2021). "The pro-inflammatory cytokines IL-6, IL-8, and TNFα possess tumor-promoting functions and increased tissue levels are associated with many types of cancer." (PMID 35145494, 2021). "On the other hand, as antitumor effectors, MCs produce mediators (e.g., tryptase, chondroitin sulfate, TNF, IL-1 and IL-6) that increase antitumor inflammatory reactions, inducing tumor apoptosis and decreasing the invasiveness of cancer cells." (PMID 34635121, 2021). "The anti-tumor effect of TC-1/A9 TAMs was mediated by both NO and TNF-α, which is in line with previously published reports of the cytotoxic potential of macrophages." (PMID 34205330, 2021). "All tumor-irradiated Sirpα−/− mice developed inflammatory responses with an elevated serum level of cytokines TNFα, IL-1β, IL-12, and IFNγ, whereas WT mice treated with the same RT regimen did not exhibit similar increases in cytokines." (PMID 34050181, 2021). "The number of tumours was dramatically decreased by the administration of etanercept, a specific TNF-α antagonist, or propagermanium, a CCR2 antagonist, even when given after treatment with AOM and DSS13,58." (PMID 34620946, 2021). "CD4+ cells can act upon the dual secretion effects of IFN-γ and TNF-α by inhibiting tumor angiogenesis." (PMID 33669271, 2021). "This combinatory immunotherapy doubled the life span of mice through the induction of a profound IFN-γ and TNF dependent tumor senescence." (PMID 34335959, 2021). "In contrast, antibiotics-induced dysbiosis promoted tumor growth via a suppressed level of TNF-α and a subsequent decrease in tumor endothelial adhesion molecules, especially intercellular adhesion molecule 1 (ICAM-1)." (PMID 34217349, 2021). "M2 type macrophages closely resemble tumor-associated macrophages (TAMs) and are characterized by increased expression of IFN-γ, CCL2, CCL5, CXCL16, CXCL10, CXCL9, TNF-α, MMP9 and IL-10, arginase-1, and peroxisome proliferator-activated receptor-γ (PPAR-γ)." (PMID 33925575, 2021). "Tumor necrosis factor alpha (TNF-α) plays important roles in processes such as immunomodulation, fever, inflammatory response, inhibition of tumor formation, and inhibition of viral replication." (PMID 34395451, 2021). "In this context, although TNF-α is utilized as a cancer immunotherapeutic agent, recently, several studies emphasized its ability to promote tumor progression and metastasis by the upregulation of the VEGF receptor." (PMID 34572719, 2021). "This is consistent with the previous report that TNFα educated TA-MSCs to recruit macrophages to promote tumor growth." (PMID 33889575, 2021). "Another group suggested the involvement of Salmonella lipopolysaccharide (LPS) in the activation and recruitment of immune cells and the subsequent production of TNF-α resulting in tumor retardation." (PMID 34829795, 2021). "Compared with the VNP20009 treatment alone, the amount of TNF‐α at the tumor in the triple therapy group was 7.9× that of the bacterial treatment group." (PMID 33854892, 2021). "5-FU with pan-caspase inhibitor IDN-7314-induced TNF-dependent necroptosis in colon cancer cells showed a better suppressive effect in tumor growth in HT-29 xenograft model compared to 5-fluorouracil alone." (PMID 33542218, 2021). "RT-qPCR analysis in the present study revealed that Rh2 regulated the expression levels of IL-1, IL-6, IL-10 and TNF-α, which inhibited tumor invasion and angiogenesis." (PMID 34452568, 2021).